TGFBR2 (transforming growth factor beta receptor 2)
Diseases named in the same sentence as TGFBR2 in open-access papers (continued):
Sharing a sentence is not in itself a finding about the gene and the disease.
tumor (continued). "When sequencing the individual metastatic nodules, we unexpectedly found that Tgfbr2 sgRNA was highly enriched and constituted ~40% of all nodules 3 weeks after tumor injection." (PMID 38997291, 2024). "TGFB ligands initiate signals by binding to the TGFB type II receptor (TGFBR2), which is known to play a crucial role in tumor progression by promoting tumor growth, invasion, and metastasis, while suppressing immune responses." (PMID 39201328, 2024). "For TGFB1 and the receptors TGFBR1 and TGFBR2, a higher expression was detectable in tumor tissue compared to vestibular nerve tissue, which is congruent with the CSF data." (PMID 39272860, 2024). "miR-17-92 exerts its inhibitory effect on the progression of CRC by reducing tumor angiogenesis which is achieved by targeting several tumor angiogenesis-inducing genes, including TGFBR2, HIF1α, and VEGFA, both in vivo and in vitro." (PMID 38534736, 2024). "Another study revealed a dual effect of TGFBR2 on BC as it can inhibit primary tumor and promote the growth of aggressive tumor." (PMID 39525474, 2024). "Many of these genes are well known, e.g., TNFRSF1A (TNFR1) or TGFBR2 which can be used against T cells to block apoptosis signaling or tumor suppressor signaling." (PMID 38459554, 2024). "Further, loss of TGFBR2, which is frequently disrupted both in EBV‐ and EBV+ NPCs, dramatically accelerated the progression and lung metastasis of NPC probably by altering tumor microenvironment." (PMID 39049720, 2024). "Research suggested that as a molecule with immune-regulatory functions, high expression of TGFBR2 can trigger innate immune responses and mitigate immune suppression, facilitating T-cell activation and infiltration, and thereby curbing tumor growth." (PMID 39364312, 2024). "We searched public databases for TGFBR1 and TGFBR2 gene expression in tumor-infiltrating immune cells." (PMID 38441961, 2024). "The inhibition of TGFBR2 has been shown to induce an immune response and promote tumor regression in certain cancers." (PMID 39201328, 2024). "In the exosome cohort CXCL12 expression was strongly correlated with EGFR status, CD44v6 was associated with tumor stage, TTF-1 expression & chromogranin protein expression and HIF1A & TGFBR2 showed positive correlation with CEA expression & CK20 expression." (PMID 38877052, 2024). "Our results showed that miR-301b-3p promoted BC progression, while TGFBR2 had a tumor-suppressive function." (PMID 39525474, 2024). "Upon the inhibition of LSD1, a reduction of the expression of the pre-mentioned genes, LOX and TGFBR2, both involved in tumor suppression, occurs." (PMID 36979853, 2023). "As TGF-β expression is induced at early tumor stages, we started ablating Tgfbr2 in ADAM12+ cells by removing doxycycline at the initiation of tumorigenesis." (PMID 37798557, 2023). "Tumor metastasis inhibition has been described upon specific genetic deletion of Tgfbr2 in myeloid cells suggesting the role of myeloid-produced TGF-β in cancer progression and possibly explaining the reduced tumor numbers in Nod2ΔLyzM mice." (PMID 37876927, 2023). "TGFBR2 can then inhibit TGF-β binding to TGF-β type II receptors on tumor cells by trapping free TGF-β." (PMID 37484024, 2023). "Taking together, our results demonstrated that USP33 promoted the tumor growth and metastasis of PC in a TGFBR2-dependent manner." (PMID 37322017, 2023). "Our data are consistent with a protumor effect of cytostasis, mediated by TGF-β, on perivascular MSCs, as selective depletion of ADAM12+ MSCs or conditional ablation of Tgfbr2 in ADAM12+ MSCs was sufficient to inhibit tumor growth." (PMID 37798557, 2023).
tumor (continued). "Further, in vivo, the xenograft tumour model indicated reduced tumour growth and reduced TGFBR2 protein levels upon circARID1A knockdown." (PMID 37891744, 2023). "GABPA acts as a tumor suppressor by stimulating TGFBR2 expression and TGFβ signaling, while L-2-HG epigenetically inhibits GABPA expression, disrupting the GABPA-TGFβ loop to drive ccRCC aggressiveness." (PMID 35549739, 2022). "TGFBR2 repression by overexpression of the entire miR-371~373 cluster decreased tumor-initiating potential in tumor-initiating cells." (PMID 36430910, 2022). "The presence of CAFs within the tumor, quantitatively depicted as FAP positivity, was strongly linked to the expression of MMP13, AKT1, TGFB3 and TGFBR2, among other factors." (PMID 35311102, 2022). "By doing so, we observe that GABPA acts as a tumor suppressor by stimulating TGFBR2 transcription and TGFβ signaling, while the oncometabolite L-2-HG epigenetically inhibits GABPA expression, disrupting the GABPA-TGFβ loop to drive ccRCC aggressiveness." (PMID 35549739, 2022). "On the other hand, enhanced EndoMT and collagen deposition were observed, and tumor regrowth was accelerated in the irradiated KP tumors of EC-specific Tgfbr2 KD (Tgfbr2 conditional KD, Tgfbr2cKD) mice, suggesting that tumors acquire radioresistance." (PMID 35130955, 2022). "ReactomeFIViz enrichment analysis in Cytoscape showed an association of seven (EDNRB, CDKN2A, VEGFD, FOS, GNG11, TGFBR2, and BIRC5) of the forty-four nodes of the LC-BC CCPs with signaling pathways related with the acquisition of tumor characteristics." (PMID 36101460, 2022). "TGFBR2 is an established tumor suppressor in several human malignancies, however, its role in ccRCC is unclear, although its downregulation has long been observed in ccRCC." (PMID 35549739, 2022). "The expression of transforming growth factor β receptor 2 (TGFBR2), a tumor suppressor, is downregulated in head and neck squamous cell cancer (HNSCC) and is generally related to EMT in LSCC." (PMID 35198889, 2022). "In consistent, ALG10 knockdown-mediated decrease of tumor-initiating ability was rescued by TGFBR2 treatment." (PMID 35680565, 2022). "For example, entinostat and sodium butyrate, two HDAC inhibitors, suppress EwS tumor growth by inducing the expression of p21 and TGFBR2, two EWSR1-FLI1-repressed genes." (PMID 35740349, 2022). "The LC-BC CCPs formed have no more than 12 nodes and identified only seven genes (EDNRB, CDKN2A, VEGFD, FOS, GNG11, TGFBR2, and BIRC5) compromised in signaling pathways associated with the acquisition of tumor characteristics." (PMID 36101460, 2022). "We found Somatic mutations in TGFBR1, TGFBR2, and TGFBR3 genes in primary tumor and metastases samples of long-responder patients." (PMID 34833459, 2021). "Decreased expression of TGFBR2 in human NSCLC was related to more invasive tumor behavior and inflammation, and the deletion of TGFBR2 in mouse airway epithelial cells promoted the formation of adenocarcinoma." (PMID 34036102, 2021). "Overall, our studies identified a novel pathway by which abnormal expression of SIX1 in cancer cells promotes tumor growth through upregulation of TGFBR2 and collagen to suppress immune cell infiltration and activation in the TME." (PMID 34782761, 2021). "To examine the potential relationship between tumor radiation-induced collagen deposition and PD-L1 expression, we generated EC-specific Tgfbr2 knockdown (EC-TGFβR2KD) mice (Tie2-Cre;Tgfbr2flox/+)." (PMID 34680381, 2021). "Recent studies have demonstrated that blocking TGF‐β signaling in CD4+T cells remodeled the tumor microenvironment and restrained cancer progression and depletion of transforming growth factor‐β receptor 2 (TGFBR2) in CD4+ T cells promoted cancer progression." (PMID 33837660, 2021). "In NK cells, we observed knockout efficiencies above 90% and show that the TGFBR2 edit significantly enhances tumor killing in a model intended to mimic the tumor microenvironment of difficult-to-treat solid tumors." (PMID 34162850, 2021).
tumor (continued). "Abrogating TGFβ signaling in TGFBR2-deleted CD4 T cells inhibited tumor growth by reorganizing the reticular vessel system in tumors." (PMID 34804029, 2021). "In the surrounding non-tumor tissues (NT), the median methylation of promoters was 75% for TGFBR2 (Range 99.68, min." (PMID 34571856, 2021). "The expression of TGF-β and TGFBR2 is elevated in co-culture studies and thus contributes to tumour cell dormancy." (PMID 34975909, 2021). "Enhanced tumor regrowth was observed after X-ray irradiation in the Tgfbr2 knockdown mice compared to the WT mice, in agreement with the patterns of collagen deposition and EndMT." (PMID 34680381, 2021). "The genes involved in tumor suppression (e.g., TGFBR2), cell proliferation, DNA repair (e.g., MSH3 and MSH6), apoptosis (e.g., BAX), etc., contain repetitive sequences in the coding regions, and alterations tend to develop in these regions." (PMID 34185173, 2021). "CircFAM120B overexpression suppressed CRC cell proliferation, migration/invasion and glycolysis metabolism and also blocked tumor growth in vivo by targeting the miR-645/TGFBR2 axis." (PMID 34381772, 2021). "Strikingly, using RISH we observed downregulation of TGFBR2 in the majority of clinical tumor samples when compared with adjacent histological normal epithelial cells and infiltrating lymphocytes." (PMID 34234122, 2021). "The genes SMAD7, TGFBR2 and TNFAIP3 were associated with both tumour suppressor and oncogenic roles." (PMID 34198662, 2021). "In the integrated genomic and transcriptome analyses, the tumor-associated genes ZBTB16, PPARG, and TGFBR2 were found to be significantly downregulated with simultaneous CNV loss." (PMID 33414372, 2021). "Further, we evaluated the methylation and expression of TGFBR2 in tumor samples through The Cancer Genome Atlas multiplatform data as well as immunohistochemistry." (PMID 32046777, 2020). "Tgfbr2 knockout inhibits angiogenesis, tumor cell proliferation, and osteoclastogenesis in metastatic bones." (PMID 32210807, 2020). "Overexpression of TGFBR2 suppressed the growth of tumor cells significantly through colony formation assays." (PMID 32046777, 2020). "CpG sites of the TGFBR2 promoter were significantly hypermethylated in tumor samples compared to normal samples." (PMID 32046777, 2020). "In 34 of these samples, the level of TGFBR2 protein was downregulated significantly in tumor tissues compared to dysplastic and normal tissue samples." (PMID 32046777, 2020). "In a subsequent study, miR‐1224‐5p was found to target TGFBR2 and repressed TGFBR2 expression, and in vitro assays showed that miR‐1224‐5p exerted tumour‐suppressive effects via targeting TGFBR2." (PMID 32319715, 2020). "For example, TGFBR2 knockout chimeric antigen receptor-modified T cells can induce Treg conversion and promote tumour regression in vivo." (PMID 33114183, 2020). "Myeloid-specific deletion of Tgfbr2 is reported to reduce migration and invasion capacity of macrophages in tumor-bearing mice as well." (PMID 33175881, 2020). "Tumor samples showed higher methylation levels compared to normal esophageal tissue samples at TGFBR2 promoter-related CpG sites." (PMID 32046777, 2020).
tumor (continued). "In a subsequent study, miR‐1224‐5p was found to target transforming growth factor‐beta receptor type 2 (TGFBR2) and repressed TGFBR2 expression, and in vitro assays showed that miR‐1224‐5p exerted tumour‐suppressive effects via targeting TGFBR2." (PMID 32319715, 2020). "We have previously reported that mice with conditional KrasG12D mutation and knockout of TGF-β receptor type II (Tgfbr2), PKF mice, develop PDAC with desmoplasia modulated by CXC chemokines that are produced by PDAC cells through tumor–stromal interaction." (PMID 30659170, 2019). "The tumor volumes of HK1‐EBV‐expressing WT TGFBR2 were significantly smaller than those of TGFBR2 mutants from day 21 (P < .05)." (PMID 31328403, 2019). "Tumor-associated myeloid cells expressed TGF-β, and specific deletion of Tgfbr2 in tumor-associated myeloid cells inhibited cancer metastasis, which indicates that the myeloid-specific TGF-β signaling is a vital part of cancer metastasis." (PMID 31010242, 2019). "Meanwhile, mutation of TGFBR2 (TGF-β receptor type II), a tumor suppressor gene, is less frequently detected in lesions in PanIN/PDAC compared with SMAD4/DPC47, both of which function in the TGF-β-SMAD signaling pathway." (PMID 30659170, 2019). "We evaluated the effect of TGFBR2 mutants on tumor growth in vivo by inoculating HK1‐EBV‐expressing WT and TGFBR2 mutants in nude mice." (PMID 31328403, 2019). "At the end of the experiment (day 48), the average of tumor volumes of TGFBR2 mutants, G253V and E290K, was 6.9‐ and 8.8‐fold, respectively, larger than that of WT TGFBR2, indicating that TGFBR2 mutants promote tumor growth." (PMID 31328403, 2019). "Similar to the effect seen in the KIC model, 2G8 decreased the survival of the mice carrying the Tgfbr2 wild‐type tumors and enhanced tumor weight." (PMID 31609088, 2019). "Altogether, these results demonstrate the successful enrichment of EVs secreted from MSI tumor cells only differing in their TGFBR2 expression status." (PMID 31454892, 2019). "For example, in mouse models of metastatic prostate cancer, soluble TGFBR2 has been deployed to trap circulating TGFβ and thus suppress tumor progression." (PMID 31428571, 2019). "These diverse pathways regulated by hypoxia eventually contribute to attenuation of TGFBR2 expression and promote tumor progression in PCa." (PMID 29699590, 2018). "Our recent studies have confirmed that the TGF-β pathway acts as a potent tumour suppressor pathway in cSCC with mutational inactivation of TGFBR1 and/or TGFBR2 occurring in ~40% of cSCC tumours." (PMID 30202019, 2018). "We analyzed the outcome of combining a deletion of the TGFß type 2 receptor (Tgfbr2) with deletion of the Pten tumor suppressor gene, which initiates tumorigenesis in the mouse prostate." (PMID 29782499, 2018). "We recently described a tumor promoting role of TGFβ signaling and TGFBR2 in human ER‐negative breast cancer." (PMID 30004628, 2018). "For the Apc mutants, we isolated tumors at 36 weeks of age, when they had extensive adenosquamous HGPIN, and at 20–24 weeks from the Apc;Tgfbr2 mutants when they first showed adverse signs of tumor burden." (PMID 29782499, 2018). "Analysis of the cell types in these tumors reveals that Tgfbr2 mutant luminal tumor cells differentiate to an intermediate cell type that has both basal and luminal characteristics, and also to basal cells." (PMID 29782499, 2018). "Undercoverage of several genes (ACVR2A, ASTE1, KIAA2018, SLC22A9, and TGFBR2) were common events across multiple tumor types, including STAD." (PMID 30281678, 2018). "We have previously shown that deletion of Tgfbr2 from mouse prostate epithelium accelerates tumor progression in the background of either a Pten or Apc null mutation." (PMID 29782499, 2018). "Uptake of these exosomes by recipient cells caused increased secretion (2–6 fold) of specific cytokines (Interleukin-4, Stem Cell Factor, Platelet-derived Growth Factor-B), depending on the TGFBR2 expression status of the tumor cell." (PMID 28376875, 2017).
tumor (continued). "Recently it was demonstrated that mice that are null for Tgfbr2 in myeloid cells express decreased levels of bFGF in the tumor environment." (PMID 28968431, 2017). "Altered TGFBR2 signaling in tumor cells can modulate a wide range of processes like epithelial-to-mesenchymal transition (EMT), migration and invasion, angiogenesis, immunomodulation, and cytokine secretion." (PMID 28376875, 2017). "We also confirmed that RAC2 is co-expressed with CD34-positive cells and that RAC1 is strongly expressed at the tumor-stroma border of Tgfbr2 cKO SCC." (PMID 28219480, 2017). "Tertiary anorectal tumors maintained the tumor hierarchy of the primary and secondary Tgfbr2 cKO SCC, and selection for CD34+ CSCs resulted in an increased ratio of CD34+ cells (75%)." (PMID 28219480, 2017). "We analyzed the lungs of tumor-bearing mice and observed that Tgfbr2 cKO SCC indeed spontaneously metastasized to the lungs with 100% frequency (n > 30 mice analyzed)." (PMID 28219480, 2017). "In support of this notion, ACVR2A and TGFBR2 were also reported by TCGA as the top two representative genes in hypermutated tumours, 77% of which were MSI7." (PMID 27302369, 2016). "Here we collected tumor samples from control and Tgfbr2 conditional knockout mice and analyzed the expression of a number of EMT marker genes." (PMID 27378170, 2016). "For example, conditional knockout of TGFBR2 in the mammary gland before tumors were established resulted in shorter median tumor latency and more pulmonary metastases." (PMID 27916872, 2016). "In Tgfbr2 conditional knockout mice, we observed downregulation of p-Smad2 in tumor cells, which correlated with increase of tumor cell apoptosis and increase of proliferation activity." (PMID 27378170, 2016). "Consistently, we detected a substantially increase of Keratin18 (K18), a differentiated tumor cell marker, in Tgfbr2 conditional knockout tumors." (PMID 27378170, 2016). "The EMT inhibitor miR-200b was shown to stimulate tumor growth in TGFBR2-null CRC by targeting CDKN1B and negatively regulating p27/kip1." (PMID 26863633, 2016). "TGFBR2 is known to act as a tumor suppressor by initiating the TGF-β signaling pathway through recruitment of TGFBR1, thus activating downstream signaling to negatively regulate cell proliferation." (PMID 27120811, 2016). "miR-17-92 and miR-192 inhibited the progression of cancers via suppressing tumour angiogenesis through targeting multiple tumour angiogenesis-inducing genes, TGFBR2 (transforming growth factor, beta receptor 2), HIF1α and VEGFA in vivo and in vitro." (PMID 27213336, 2016). "Interest in the relationship between miR-135b and TGFBR2 was also supported by the recent identification of this miRNA as a candidate oncogene and of TGFBR2 as a tumor suppressor in CRC." (PMID 26061281, 2015). "Paradoxically, however, ablation of TGFβ receptor 2 (TGFBR2) in prostatic fibroblasts resulted in spontaneous neoplasia, illustrating a tumor-suppressive function of TGFβ signaling in early tumor development." (PMID 26375444, 2015). "Significantly higher TGFB1 and TGFB3 mRNA levels and lower TGFBR2 mRNA levels were observed in primary tumours compared with their paired normal tissues." (PMID 26703884, 2015). "The increased tumor latency was also opposite to MMTV-PyMT/TGFβRII-KO mice with deletion of Tgfbr2 in the mammary epithelium, as previously studied in our laboratory." (PMID 25280532, 2014). "Taken together, TGFBR2 played an important role in miR-301a mediated tumor migration and invasion in CRC." (PMID 25551793, 2014). "Supporting this, we observed an inverse correlation between miR-301a and TGFBR2 protein expression in CRC tumor tissues." (PMID 25551793, 2014). "In previous work we have demonstrated that transient transfection of TGFBR2 into HCT116 cells, deficient for this receptor, led to alterations of cell surface glycosylation in these MSI tumor cells." (PMID 23468914, 2013).